TNF (tumor necrosis factor)
Diseases named in the same sentence as TNF in open-access papers (continued):
Sharing a sentence is not in itself a finding about the gene and the disease.
tumor (continued). "In the presence of tumor cells, or following stimulation with TCR agonists, NKG2D ligands, cytokines (such as IL-12 and IL-18), or DNAM-1 engagement, human γδ T cells produce IFN-γ and TNF-α." (PMID 25538706, 2014). "TGF-β increases the expression of PTHrP and other growth factors like IL-1, IL-6, IL-8, IL-11, prostaglandin E-2 (PGE2), macrophage colony stimulating factor (M-CSF), and tumor necrosis factor α (TNF-α) by direct impact on cancer cells, resulting in enhanced tumor growth in BM." (PMID 25147739, 2014). "It is reported that PRDX1 could be secreted from tumor cells and extracellular PRDX1 could induce the secretion of proinflammatory cytokines such as TNF-α and IL-6." (PMID 25024510, 2014). "Although TAMs contribute significantly to production of VEGF, IL-1β, TNF-α, IL-6, IL-23, IL-8, MMPs which have pro-angiogenic and growth attributes, specific molecular pathways in macrophages that immunoedit tumor growth are not well defined." (PMID 24842612, 2014). "As results of tumor cell inoculation, marked decreases of spleen and submandibular lymph node weights, serum IFN-γ, splenic TNF-α, IL-1β and IL-10 contents, splenocytes and peritoneal NK cell activities were observed with histopathological atrophic changes of spleen and submandibular lymph nodes." (PMID 25477992, 2014). "Furthermore, the percentage of liver tissue replaced by tumor cells was significantly lower in CT26 + IR + Enbrel and CT26 + IR + TNF-α pretreatment groups compared to the CT26 + IR group." (PMID 24397824, 2014). "As already proposed by and confirmed in this study combined IL-4 and TNFα treatment exerts a synergistic effect on the increase of HLA class I antigen expression in RCC cells, which might enhance T cell-based anti-tumor responses." (PMID 24885059, 2014). "However, in a mouse model of ovarian cancer, TNF-α can also stimulate the secretion of other cytokines like IL-17 by CD4+ T cells and promote tumor growth indirectly." (PMID 24901008, 2014). "We found minimal detection of pro-inflammatory cytokines in the serum of the NT group (normal mice without tumor), whereas, tumor bearing mice had significantly elevated levels of TNF-α, IL-6 and IL-1β." (PMID 24885825, 2014). "The secreted IFN-γ and TNF-α by the NK cells or the macrophage, particularly the IFN-γ, can react to the NK cells, increase its cytotoxic activity, and play a key role in killing tumor cells or induce tumor cell apoptosis." (PMID 24444073, 2014). "Platycodin D showed favorable cytotoxic effects on the H520 cells, and also dose-dependently decreased the tumor volumes and weights with increases of apoptotic cells (caspase-3 and PARP immunopositive cells), iNOS and TNF-α immunoreactivities, decreases of COX-2 immunoreactivities in tumor masses." (PMID 25477992, 2014). "The microenvironment of tumours are typically rich in proinflammatory mediators, such as Tumour Necrosis Factor (TNF)-α, Interleukin (IL)-1, IL-6, IL-8, cyclooxygenases-2 (COX-2), and inducible nitrogen synthesis (iNOS) which are essential components of the tumour initiation and promotion." (PMID 24734105, 2014). "Among tumor-derived factors that activate fibroblasts are TGFβ, PGE, TNF, IFNγ, and IL6." (PMID 24818101, 2014). "The addition of birinapant indeed led to a further enhancement of both TRAIL/zVAD/CHX- and TNF/zVAD/CHX-induced programmed necrosis in all sensitive tumor cell lines, but not in the resistant tumor cell line KNS-62." (PMID 24507727, 2014). "TNF-α synthesis followed IL-12 production; either physical activity or the presence of a tumor increased TNF-α expression compared with the no tumor/non-trained control group (P=0.0273 and P=0.0127, respectively)." (PMID 24520305, 2014). "In this study, we used TNF-α to induce apoptosis and we chose the cancer cell line MCF-7 because, unlike normal cells, tumor cells are sensitive to TNF-α." (PMID 24885534, 2014).
tumor (continued). "First, we tested whether activation of 18Co cells with TNF, or with LPS, a known inducer of inflammatory mediators, alters their ability to activate STAT1 activity and their crosstalk with tumor cells." (PMID 24818101, 2014). "Our previous studies showed that cytokine signals, including TNFα, TGF-β, and VEGF, derived from the primary tumor site affected lung endothelial and epithelial cells to produce a pre-metastatic phase that facilitated actual tumor cell migration." (PMID 25268596, 2014). "Differentiation towards an M1 macrophage phenotype typically occurs following activation by interferon-γ (IFN-γ), granulocyte-macrophage colony-stimulating factor (GM-CSF), tumor necrosis factor (TNF), or lipopolysaccharide (LPS), resulting in a host defense or tumor resistance phenotype." (PMID 24531335, 2014). "Like TNF-α, IL-6 facilitates tumor development by promoting conversion of noncancer cells into tumor stem cells." (PMID 24901008, 2014). "TNF-α and its receptors, TNFRSF1A and TNFRSF1B belong to the TNF-TNFR superfamily, and the interaction of these genes regulates inflammation and increases the invasive activity and metastatic potential of tumor cells." (PMID 25010932, 2014). "Cytokines, such as interleukin-2 (IL-2), interferon-α (IFN-α), and tumor necrosis factor-α (TNF-α) have been used non-specifically to stimulate an anti-tumor response." (PMID 24860566, 2014). "In addition, the levels of TNF-α and IFN-γ were significantly increased, whereas the levels of IL-10 and TGF-β were significantly decreased in tumor-bearing mice treated with APS." (PMID 25251192, 2014). "Although TNF-α had been related to chronic inflammation and tumor promotion, we have not seen ameliorated symptoms and immune response against cancer from KO mice." (PMID 25268644, 2014). "IFN-γ and TNF-α reversed the effect of CXCL1, but were less efficient in suppressing tumor growth." (PMID 25587026, 2014). "Using an inducible histone 2B-GFP fusion protein as a tracer of cell divisional history, we determined that tumor necrosis factor (TNF), which is a classical pro-inflammatory cytokine, enlarged the CSC pool of GFP-positive label-retaining cells (LRCs) in tumor-like melanospheres." (PMID 25223735, 2014). "On the contrary, gemcitabine administered mice showed significant (P < 0.05) decreases of the splenic TNF-α and IL-1β, and nonsignificant but dramatic decreases of splenic IL-10 contents as compared with tumor-bearing control mice, respectively." (PMID 25477992, 2014). "Cytokines such as TNF-α could also induce EMT through Snail stabilization and increased migration and invasion of tumor cells." (PMID 25413472, 2014). "Exercise training in mice with tumors further increased TNF-α expression beyond that which was observed in the tumor/non-trained group (P=0.0417)." (PMID 24520305, 2014). "SCP-60 exhibited strong anti-tumor activity in vivo, while SCP-60 at 100 mg/ kg also significantly increased the thymic and spleen indices of S180 mice, and strongly promoted the secretion of IL-2, TNF-α and IFN-γ." (PMID 25068783, 2014). "These cytokines, such as tumor necrosis factor-α (TNF-α), interleukin-6 (IL-6), IL-8, IL-10, and macrophage inflammatory protein 1 (MIP-1), have been shown to stimulate angiogenesis and promote IR, as well as being pivotal to tumor development." (PMID 25069390, 2014). "Some reports suggest possible linkage disequilibrium between HSP70 and TNF SNPs, since TNF and HSP70 gene families are located just 600 kb apart from each other, which indicate that TNF and HSP70 may act as endogenous tumor promoters in vivo." (PMID 25143984, 2014). "In addition, PMS1077 was also found to suppress the TNF-α induced expression of NF-κB regulated anti-apoptotic genes, leading to sensitization of TNF-α induced apoptosis in tumor cells." (PMID 23593410, 2013).
tumor (continued). "ES cells were also shown to be sensitive to natural killer (NK) cells and to tumor necrosis factor (TNF)-related apoptosis-inducing ligand (TRAIL), a member of the TNF superfamily with strong anti-tumor activity and minimal toxicity to most normal cells and tissues." (PMID 23508552, 2013). "By activating TLRs, these miRNAs trigger the NF-kappaB pathway which ultimately leads to an increased production of interleukin-6 (IL-6) and tumor necrosis factor-alpha (TNF-alpha) by the immune cells, leading to increased tumor growth and metastatic potential." (PMID 23802096, 2013). "In addition, the transcription factor NF-κB, a downstream effector of tumor necrosis factor α (TNF-α), has been suggested to affect skin carcinogenesis." (PMID 24403255, 2013). "At day 29 after cell inoculation, volume of grafted tumor in Hep-2/TIC group, Hep-2/CD group, Hep-2/TNF-α group and Hep-2/0 group was 80.47±33.74 mm3, 135.5±14.83 mm3, 525.8±40.70 mm3 and 678.3±52.34 mm3, respectively; significant difference was seen between each two of them (P<0.05)." (PMID 23593411, 2013). "This degree of tumor hypoxia could prime the tumor vasculature for adherence/vaso-occlusion by SSRBCs by stimulating tumor cell synthesis of proangiogenic/pro-inflammatory proteins such as VEGF and TNFα." (PMID 23326340, 2013). "The biological mechanisms linking tumor aggressiveness in IL-6, IL-8 and TNF- α are not clearly understood." (PMID 23637926, 2013). "It is well known that TNF can play both tumor-promoting and tumor-suppressing roles, but AiA has not been investigated in this context." (PMID 24066226, 2013). "The tumor cells showed very little gelatinolytic capacity and in vitro neither their invasive nor their adhesive capabilities were modulated by TNF stimulation." (PMID 24098720, 2013). "And then TNFα stabilized Snail transfer into the nucleus, decreases epithelial makers E-cadherin and ZO-1 expressions, increases mesenchymal makers N-cadherin and fibronectin expressions, finally induces EMT and promotes tumor metastasis." (PMID 23431386, 2013). "However, as already outlined for the TNF/TNFR1 system, TRAIL-signalling in apoptosis resistant tumour cells can result in promotion of tumour metastasis and upregulation of pro-inflammatory factors." (PMID 23852022, 2013). "TNF-α was not used to activate NF-κB, rather, we relied on the pro-inflammatory tumor microenvironment to trigger the initial NF-κB activation." (PMID 24244348, 2013). "When doing this analysis, we were aware of the fact that MCF-7 cells are sensitive to TNFα cytotoxicity, and accordingly our routine procedure of TNFα + Estrogen + EGF stimulation for three days has led to death of approximately 40% of the tumor cells." (PMID 24369447, 2013). "The synchronous evaluation of 12 cytokines showed that preoperative plasma levels of the proinflammatory cytokines IL-6, IL-8, IL-1β, TNFα were significantly lower in healthy donors versus CRC patients and that such differences progressively increase with tumor stage." (PMID 24040252, 2013). "In contrast, the reciprocal incubation of U937-derived sups with both TNFα-stimulated tumor cells did not affect MMP-9 secretion, and elevated VEGF secretion by about 2.5-folds (p < 0.001)." (PMID 23874303, 2013). "In our study, it is consistent with previous studies, high doses of TNF-α (100 or 1000 ng/ml) enhanced serum starvation-induced apoptosis, which maybe due to the direct killing effect of TNF-α on tumor cells." (PMID 24066693, 2013). "Expression of chemokine for monocytes (CSF-1 and CCL-2) were low in tumor cells from EGCG-treated mice, and cytokines of TAM was skewed from M2- into M1-like phenotype by EGCG as evidenced by decreased IL-6 and TGF-β and increased TNF-α." (PMID 24044575, 2013). "The cooperative action of TGF-β and TNF-α on EMT attracts increasing attention since it reflects the cancer microenvironment infiltrated with inflammatory cells, and provides a model where inflammatory signals enhance tumor progression." (PMID 23437179, 2013).
tumor (continued). "The major TNF receptor, TNFR1, is ubiquitously expressed on normal cells, as a consequence of which soluble TNF has no or only limited tumor binding selectivity and considerable toxicity." (PMID 23840967, 2013). "Tumor Necrosis Factor-alpha (TNF-α) can inhibit tumor progress through different signal pathways, such as cells apoptosis, killing cells by direct cytotoxicity effect or damaging the microvasculature of tumor tissue." (PMID 23593411, 2013). "To test whether TNF also influences Panc02-FUGLW tumor growth and metastasis, we treated tumor bearing mice with recombinant human TNF, which only binds to murine TNFR1, every other day for three weeks following tumor cell inoculation." (PMID 24098720, 2013). "Carcinoma cells and HaCaT cells were treated with tumor stimulus, TGF-β, TNF-α or EGF." (PMID 23936352, 2013). "Hypoxia, in turn, supports tumor angiogenesis through the hypoxia-inducible transcription factors (HIF), and further elevates the expression of pro-angiogenic molecules, such as VEGF, TNF (tumor necrosis factor), and PDGF (platelet-derived growth factor)." (PMID 23967403, 2013). "Tumor necrosis factor-related apoptosis-inducing ligand (TRAIL), a member of the tumor necrosis factor (TNF) superfamilies, is a candidate for cancer therapy due to its ability to selectively trigger apoptosis in tumor cells but not normal cells." (PMID 23826494, 2013). "Indeed, through their ability to produce cytokines such as tumor necrosis factor (TNF)-α and stromal cell-derived factor 1 (SDF-1), hypoxic tumor cells induce the homing of bone marrow-derived CD45+ myeloid cells to tumor areas." (PMID 24400010, 2013). "Moreover, SAgs activated T cells and monocytes also produce various cytolytic cytokines notably IFN-γ, TNF-α, IL-2 which alone or together with nitrous oxide can induce cytotoxicity in both MHCII+ and MHCII- tumor cells." (PMID 23964349, 2013). "On serial section, CYGB, PI3K, p-Akt, IL-6, TNFα and VEGF could be detected in the same area of tumor cells, at least in a part of them." (PMID 23688241, 2013). "This was corroborated by increased IFN-γ and TNF-α released into the supernatant culture medium from NK cells in contact with GBM cells compared to supernatants from tumor cells only, (IFN-γ: One-Way ANOVA6.54, p=0.03; n=11; and TNFα: One-Way ANOVA 9.59, p=0.0083; n=11)." (PMID 24127551, 2013). "We show that NT5E is a target of the TNF-α signaling in vitro; the tumor suppressor PPARγ acts as a novel NT5E antagonist that positively and concomitantly regulates DCBLD2 in a cancer cell context-dependent manner." (PMID 24133572, 2013). "Our previously studies indicated the inhibitory effect of S. striata extract on pro-inflammatory mediators production by macrophages including Nitric Oxide (NO), TNF-α, IL-1β and PGE2 and also suppressive effect on matrix metalloproteinases in Wehi-164 tumor cell line in vitro." (PMID 23837463, 2013). "OA increased TNF-α gene expression in mouse skin and induced TNF-α release from cultured cells in vitro, as do many other irritant materials, including the “classical” tumour promoter TPA." (PMID 23381142, 2013). "We also observed that BMDM differentiated from the BMC of orlistat-administered tumor-bearing mice showed augmented phagocytosis, tumoricidal activity, expression of cell surface receptors like CD11c, TLR-2 and production of ROS, NO, IL-1 and TNF-α." (PMID 24349275, 2013). "Our study shows that hypothermia promotes EMT and tumor immune evasion by TGF-β1 dependent and independent ways, respectively, and that adipocytes activated by a hypothermic environment drive malignant progression by increasing TNF-α and VEGF levels." (PMID 24015203, 2013). "However, signaling pathways that mediate the interactions between tumor cells and the innate immune system (JNK, JAK-STAT, TNF, Toll/Imd/TLR) as well as the way these pathways interact with each other are highly conserved in flies." (PMID 24392358, 2013).
tumor (continued). "Further supporting the ability of TNFα + Estrogen + EGF stimulation to induce EMT was the prominent increase in the expression of the known EMT activators Zeb1, Snail, and Slug in the tumor cells (the EMT regulator twist was down-regulated; data not shown)." (PMID 24369447, 2013). "As a result of TNFα + Estrogen + EGF stimulation, new cell subtypes have dominated the tumor cell population, expressing high levels of VLA6 and of the metastasis-related adhesion molecules CD44 and β1, accompanied by high levels of CXCL8, CCL2, and MMPs that were released by the cells." (PMID 24369447, 2013). "This high dose of TNF triggers endothelial cell apoptosis and subsequent destruction of the tumor vasculature, whereas normal blood vasculature is not affected." (PMID 23840967, 2013). "Herein, we show that fluvastatin does not affect the release of FasL and TNFα and the consequent killing of tumor target cells due to these soluble factors." (PMID 23667543, 2013). "Despite this, we did not observe increased metastasis of the primary Panc02 tumor to the liver upon exogenous TNF treatment." (PMID 24098720, 2013). "TNF-α is an inflammatory cytokine that regulates cell proliferation and cell death, and resistance to TNF-α-induced apoptosis may lead to tumor formation and growth." (PMID 24327924, 2013). "The net balance of positive and negative intercellular signaling dictates tumor cell proliferation and survival, and proteins of the tumor necrosis factor (TNF) superfamily loom large in this array of regulatory signaling inputs." (PMID 24130833, 2013). "In addition to 51Cr release experiments, the killing of SKBR3 tumor cells was evidenced by their Annexin V+ 7-AAD− profile, while the state of iNKT cell activation was evaluated by CD107a expression, and secretion of TNFα and IFNγ." (PMID 23242316, 2013). "To confirm that these data are not phenomena of cultured cell lines, we assessed TNF-α-induced STAT3 activation in human GBM cells maintained in an environment similar to the tumor microenvironment." (PMID 24244348, 2013). "Additionally, autocrine TGF-β signaling is involved in the maintenance and survival of stem-like cell populations, and exposure of tumor cells to TGF-β and tumor necrosis factor-α induces EMT, which generates tumor cells with stem cell properties." (PMID 24325450, 2013). "Application of highly diluted homeopathic medicines to macrophages has been shown to suppress previously elevated levels of TNF-α, increase the activity of NADPH oxidase and the expression of inducible nitric oxide synthase (iNOS), and induce differential gene expression in tumor conditions." (PMID 24053127, 2013). "We therefore, collected sups from TNFα-stimulated single cultures of each of the tumor cells, and incubated them diluted in medium at a ratio of 1:4 with U937 cells, with or without the presence of TNFα." (PMID 23874303, 2013). "Through the production of VEGFA, TGFβ, and tumor necrosis factor-α (TNFα), tumor cells enhance the expression of the chemoattractants S100A8 and S100A9 in lung endothelium and myeloid cells, which in turn promote tumor cell homing and adhesion to the metastatic site." (PMID 22482059, 2012). "Alternatively, the co-factors and adaptors activated by MFG-E8 may interfere with the TNF-mediated inflammatory signal cascade and RIP kinase activities in dying tumor cells." (PMID 22761839, 2012). "The immune cells from pulchellin-treated mice also produced statistically higher concentrations of TNF-α by PEC cells, and IL-4, IFN-γ and IL-10 by splenocytes, and lower concentrations of IL-6 (PEC cells) and TGF-β (splenocytes), than the cells from tumor control mice." (PMID 22827934, 2012). "After 72 h of incubation, we observed increased levels of IFN-γ, TNF-α, IL-10, IL-2, and TGF-β1 in the supernatant of RB tumor cell and PBMC cultures incubated with 1 μg/ml of EpCAM×CD3 antibody compared to an incubation with CD3 or EpCAM monoclonal antibodies alone." (PMID 22328825, 2012).